BRAF (B-Raf proto-oncogene, serine/threonine kinase)
Diseases named in the same sentence as BRAF in open-access papers (continued):
Sharing a sentence is not in itself a finding about the gene and the disease.
melanoma (continued). "The clinical introduction of BRAF inhibitors (BRAFi), and later their combination with MEK inhibitors (MEKi), has substantially improved outcomes in patients with BRAF-mutant melanoma, outperforming previous chemotherapy-based treatments." (PMID 40872623, 2025). "When MITF is upregulated in response to BRAF/MEK inhibition, it promotes cell survival, differentiation, and metabolic adaptations that enable melanoma cells to escape drug-induced cell death." (PMID 40872623, 2025). "Preclinical studies indicate that combining CQ or HCQ with BRAF inhibitors, MEK inhibitors, or immunotherapy can enhance the cytotoxic effects of these drugs on melanoma cells (NCT01844505)." (PMID 40331942, 2025). "Meanwhile, the combination of BRAF inhibitor and MEK inhibitor was shown to induce GSDME-dependent pyroptosis in mouse melanoma cells and increase T cell infiltration." (PMID 40645933, 2025). "For instance, in human melanocytic nevi, which are benign lesions harboring activated oncogenes such as BRAF, OIS acts as a barrier to prevent further progression to melanoma." (PMID 40781676, 2025). "Serval inhibitors for BRAF of the MAPK pathway, such as Vemurafenib and Dabrafenib, have shown effective results against melanomas." (PMID 40149342, 2025). "In conclusion, our study revealed that actionable gene alterations in BRAF, NRAS, KIT, and NF1 are common in Japanese patients with melanomas." (PMID 39823560, 2025). "In conclusion, consistent with previous studies, dual BRAF/MEK inhibition with dabrafenib and trametinib induces profound metabolic reprogramming in YUMM1.7 melanoma cells." (PMID 39984334, 2025). "The efficacy of BRAF and MEK inhibition has been demonstrated in adult populations for melanoma and more recently in non-small cell lung cancer." (PMID 39671021, 2025). "Melanoma patients, despite having BRAF mutation, show varied responses to vemurafenib; however, no studies to date have analyzed the molecular relationships between vemurafenib tolerance thresholds and the specific metabolic pathways utilized to ensure melanoma survival." (PMID 40558548, 2025). "Over the past decade, PD-1-based immune checkpoint inhibitors (ICI) and targeted therapies (TT) with BRAF and MEK inhibitors transformed melanoma treatment." (PMID 39673834, 2025). "Systemic therapies available to patients with resected stage III melanoma in the adjuvant setting include immune checkpoint inhibitors (ICI) and BRAF/MEK inhibitors (BRAFi/MEKi)." (PMID 41342263, 2025). "Targeted therapies for melanoma MEK and BRAF inhibitors fail due to the development of chemoresistance." (PMID 40135438, 2025). "The rationale for neoadjuvant targeted therapy (BRAF and MEK inhibitors) in melanoma centers on achieving rapid reduction in tumor burden, improving resectability, and potentially enhancing long-term outcomes." (PMID 40647451, 2025). "The novel C‐terminal HSP90 inhibitor KU757 effectively targets primary and BRAF and MEK inhibitor‐resistant melanoma cells equally by affecting oxidative phosphorylation and the cell cycle." (PMID 40135438, 2025). "Mutations in the Aurka inhibitor PPP6 C (protein phosphatase 6 catalytic subunit) gene are also typical in BRAF and NRAS mutant melanomas." (PMID 40361349, 2025). "Moreover, combination therapy using BRAF inhibitors in conjunction with inhibitors targeting the down‐stream protein MEK has been proven to significantly prolong the overall survival of melanoma patients with BRAF V600 mutations, which represents about 50% of all melanoma cases." (PMID 41199020, 2025). "This study aims to address this critical gap by conducting a bibliometric analysis of global research on BRAF and MEK inhibitor resistance in melanoma." (PMID 39897423, 2025). "In melanoma, PKA can modulate BRAF and CRAF, and overexpression of PKA induces resistance to MAPK inhibition." (PMID 39658088, 2025).
melanoma (continued). "These patterns underscore the progressive development and global expansion of research on resistance to BRAF and MEK inhibitors in melanoma." (PMID 39897423, 2025). "Targeting these pathways, particularly mTOR signaling to overcome the inevitable acquired resistance to BRAF and MEK inhibition in melanoma, has been investigated." (PMID 39941158, 2025). "A recent phase I study showed that combinations of BRAF inhibitor vemurafenib, MEK inhibitor cobimetinib, and XL888 had significant toxicity in patients with advanced melanoma." (PMID 41425251, 2025). "In the current therapeutic landscape, immune checkpoint inhibitors (ICIs) targeting PD-1 and CTLA-4, as well as targeted therapies against MAPK pathway components (e.g., BRAF and MEK inhibitors), have become standard-of-care treatments in melanoma." (PMID 40573249, 2025). "This study provides a comprehensive bibliometric analysis of global research on BRAF and MEK inhibitor resistance in melanoma, highlighting key trends, influential contributors, and emerging research priorities." (PMID 39897423, 2025). "SSM: Superficial spreading melanoma; NM: Nodular melanoma; LMM: Lentigo maligna melanoma; ALM: Acral lentiginous melanoma, DM: Desmoplastic melanoma; BRAF: B-Raf proto-oncogene, serine/threonine kinase; KIT: KIT proto-oncogene receptor tyrosine kinase." (PMID 40984902, 2025). "Targeted therapies, including FDA (Food and Drug Administration)-approved BRAF-inhibitors vemurafenib and dabrafenib, have significantly improved survival rates in BRAFV600E melanoma patients." (PMID 40141318, 2025). "Several BRAF and MEK inhibitors, such as vemurafinib and dabrafenib, are used in various cancers, including melanomas, thyroid cancers, lung cancers, and many others." (PMID 41516092, 2025). "Targeted treatments with BRAF and MEK inhibitors have significantly improved progression-free and overall survival in melanoma patients." (PMID 40332392, 2025). "The introduction of modern systemic therapies such as BRAF/MEK-directed TT and PD-1-based ICI has led to a significant improvement in overall survival of stage IV melanoma patients with distant metastases." (PMID 40028330, 2025). "Several of these fusions, such as the mentioned AGK::BRAF, KIAA1549::BRAF, and MKRN1::BRAF, have been previously reported in melanoma and other solid tumors." (PMID 40737104, 2025). "Actionable gene alterations in BRAF, NRAS, NF1, and KIT are common in Japanese patients with melanoma." (PMID 39823560, 2025). "We advocate for stronger partnerships between institutions across borders to break down academic barriers and foster the global exchange of knowledge, which is critical for advancing research on BRAF and MEK inhibitor resistance in melanoma." (PMID 39897423, 2025). "Recent advances in treatment options, including immune checkpoint inhibitors (ICIs) and BRAF and MEK inhibitors (BRAFi + MEKi), have contributed to a decline in melanoma-related mortality." (PMID 40192945, 2025). "BRAF/MEK inhibitors (BRAFi/MEKi) and PD-1 and CTLA-4 immune checkpoint inhibitors (ICI) have revolutionized malignant melanoma treatment and improved patients’ clinical outcome significantly." (PMID 40310541, 2025). "One of the resistance mechanisms to BRAF/MEK inhibitors involves the up-regulation of pro-survival factors, which enable melanoma cells to evade apoptosis even when ERK is completely or efficiently inhibited." (PMID 40063190, 2025). "Furthermore, as there is no definitive evidence that ICI therapy results in superior overall survival than anti-BRAF therapy in the adjuvant treatment of BRAF-positive melanoma, clinicians might consider anti-BRAF treatments for individuals with a high risk of irAEs." (PMID 40642097, 2025). "To investigate immune responses after conformal RT, we established two melanoma tumors, i.e., a subcutaneously engrafted B16F1 (B16) and a genetically induced BrafCAxPtenf/fxTyrCreER (BRaf/Pten) tumors." (PMID 40146036, 2025).
melanoma (continued). "Although signaling pathways, such as the BRAF and MAPK pathways, have been demonstrated to be involved in regulating melanoma cell behavior, their complex regulatory roles in immunotherapy resistance require further investigation." (PMID 40539068, 2025). "Genetically, melanomas represent a heterogeneous population of tumours with genomic aberrations most commonly affecting NRAS (15%–20%) and BRAF (40%–50%)." (PMID 40135438, 2025). "When BRAF or MEK is inhibited, the feedback mechanisms in melanoma cells trigger compensatory pathways to reactivate or increase MITF expression." (PMID 40872623, 2025). "The double BRAF-MEK inhibition, recommended in melanoma, targets an RTK and one of its downstream effectors simultaneously." (PMID 40282457, 2025). "Treatment with BRAF inhibitors has been shown to increase NK-cell infiltration and reduce Treg and MDSC levels in mouse models of BRAF-mutant melanoma." (PMID 39998776, 2025). "To investigate the impact of the treatments on key signaling pathways involved in melanoma progression, we evaluated the expression and activation status of ERBB2, BRAF, PI3K, AKT1, and mTOR by immunofluorescence analysis." (PMID 40806647, 2025). "AKT3 promotes resistance to apoptosis in BRAF-targeted melanoma cells, and FGF/FGFR signaling supports melanoma survival and therapy resistance." (PMID 41000875, 2025). "Using BRAF and MEK inhibitors which are small molecule inhibitors, helps to stop diseases related to melanoma in patients with these gene abnormalities." (PMID 41049012, 2025). "BRAF inhibitors combined with MEK inhibitors have shown promising potential as neoadjuvant therapy in other tumors, such as locally advanced melanoma or metastatic thyroid cancer; however, the evidence in patients with NSCLC remains very limited." (PMID 41480531, 2025). "These trends reflect the evolving priorities and innovative approaches shaping the field of resistance to BRAF and MEK inhibitors in melanoma." (PMID 39897423, 2025). "Elevated YAP1 expression is associated with this resistance in preclinical models and has been correlated with poor survival in patient cohorts with melanoma and NSCLC treated with BRAF inhibitors." (PMID 40332392, 2025). "In the TCGA cohort, the four distinct subtypes of melanoma (TCGA-SKCM), BRAF, NRAS, triple wild type, and NF1 put together, constitute only 25% of the samples, leaving ~75% with no clear mutation association." (PMID 41368197, 2025). "Mechanistically, we show that ATAD2 inhibition activates both distinct and common tumor-suppressive pathways in BRAF and NRAS mutant melanoma." (PMID 41331524, 2025). "Employing MeRLin in a melanoma model that recapitulates the clinical emergence of BRAF/MEK inhibitor (BRAFi/MEKi) resistance, we traced the clonal origins and transcriptional states of thousands of individual melanoma cells as they acquired resistance in vivo." (PMID 41000875, 2025). "The observation that AT2R antagonists potentiate the effects of BRAF and MEK inhibitors underscores the potential benefits of combining renin–angiotensin system inhibitors with targeted therapies for melanoma." (PMID 39941158, 2025). "His prolific output and high citation counts affirm his pivotal role as a leading figure in the field, making significant contributions to advancing research and shaping the academic discourse on BRAF and MEK inhibitor resistance in melanoma." (PMID 39897423, 2025). "Studying the dormancy marker, NR2F1, in response to BRAF and MEK inhibitors reveals its role in promoting drug tolerance and highlights the use of mTORC1 inhibitors as a potential strategy for melanoma treatment." (PMID 40955663, 2025). "Since the 2010s, the introduction of BRAF and MEK inhibitors and immune checkpoint inhibitors targeting CTLA‐4 and PD‐1/PD‐L1 has revolutionised treatment strategies for melanoma." (PMID 40898695, 2025).
melanoma (continued). "50% of patients develop resistance to BRAF and MEK inhibitors within 6–7 months of initiating treatment, underscoring the persistence of melanoma as a significant clinical challenge." (PMID 39897423, 2025). "This study aims to perform a comprehensive bibliometric analysis of global research on BRAF and MEK inhibitor resistance in melanoma, identifying key research trends, influential contributors, and emerging themes from 2003 to 2024." (PMID 39897423, 2025). "BRAF-mutant melanoma with acquired resistance to vemurafenib showed increased levels of DNMT1, which is an eminent epigenetic factor in melanoma progression." (PMID 39935431, 2025). "Over the last decade, two important strategies have been developed for the systemic treatment of melanoma: PD-1 based immune checkpoint inhibition (ICI) and targeted therapy (TT) with BRAF and MEK in-hibitors." (PMID 39673834, 2025). "Resistance to BRAF and MEK inhibitors in melanoma has been correlated with elevated levels of CD20 and IGF-1 transcripts in the TME, alongside increased IGF-1 expression by B cells." (PMID 41285707, 2025). "Keyword analysis provides a comprehensive overview of the research landscape and emerging trends in BRAF and MEK inhibitor resistance in melanoma." (PMID 39897423, 2025). "Top 10 most prolific and co-cited authors in BRAF and MEK inhibitor resistance research in melanoma." (PMID 39897423, 2025). "In the investigated cohort, a second course of adjuvant melanoma treatment is feasible and provides similar RFS compared to an initial course of adjuvant therapy using BRAF + MEK inhibitors; however, RFS2 is reduced for PD‐1 antibodies." (PMID 40331873, 2025). "The top 10 institutions publishing literature in BRAF and MEK inhibitor resistance research in melanoma." (PMID 39897423, 2025). "This gap underscores the need for a systematic bibliometric evaluation to better understand the state of research on BRAF and MEK inhibitor resistance in melanoma, identify knowledge gaps, and inform future therapeutic strategies." (PMID 39897423, 2025). "The MAPK pathway is upregulated in 66% of melanomas, and many harbor mutated BRAF with the activating BRAF V600E mutation; thus, targeting the RAS/RAF/mitogen-activated protein (MAP)/extracellular signal-regulated kinase (ERK) kinase (MEK)/ERK pathway may be effective in melanoma." (PMID 40761343, 2025). "For instance, while BRAF and MEK inhibitors show synergistic potential with immunotherapy in melanoma, this combination has limited efficacy in lung cancer." (PMID 40332392, 2025). "Although BRAF mutant melanoma has attracted much attention, NRAS was actually the first melanoma oncogene to be identified." (PMID 41160271, 2025). "Using CiteSpace, we identified the top 50 references with the strongest citation bursts in the field of BRAF and MEK inhibitor resistance in melanoma." (PMID 39897423, 2025). "Both compounds exhibited favorable binding energies with several targets, including PI3K, AKT1, mTOR, BRAF, and ERBB2, all of which are critical regulators of cell proliferation and survival in melanoma." (PMID 40806647, 2025). "MEK inhibitors such as trametinib and cobimetinib are downstream of BRAF by targeting MEK1 and MEK2, critical components of the MAPK signaling pathway involved in melanoma progression." (PMID 40142960, 2025). "Molecular parallels between COM and human melanoma, particularly MAPK pathway alterations and genes like BRAF, NRAS, MITF, and NF1, further support this study’s relevance." (PMID 40647405, 2025). "Genetic or pharmacological inhibition of ATAD2 suppresses the growth and metastasis of BRAF and NRAS mutant melanoma." (PMID 41331524, 2025). "While surgical excision remains the primary treatment method, systemic treatments such as PD-1 and CTLA-4 inhibitors, BRAF/MEK-targeted agents, and, in some cases, chemotherapy or radiation therapy play a crucial role in managing malignant melanoma." (PMID 40282947, 2025).
melanoma (continued). "Recent advances, including the introduction of BRAF/MEK inhibitors and immunotherapy, have improved outcomes in advanced melanoma; however, many patients develop resistance, either intrinsically or throughout treatment." (PMID 40565936, 2025). "In a BRAF mutant, PTEN-null mouse model of melanoma, combination inhibition with anti-PI3Kβ inhibitor and anti-PD-1 antibody improved response and survival compared to either monotherapy." (PMID 40362630, 2025). "In melanoma, PAK1 hyperactivation promotes cell survival, proliferation, and immune evasion, contributing to resistance against BRAF and MEK inhibitors." (PMID 40001545, 2025). "The melanoma cells in this study were derived from human NRAS-mutant tumors, which are difficult to treat with targeted kinase inhibitors compared to BRAF-mutant tumors." (PMID 39996721, 2025). "In order to support the involvement of CK2 in melanoma therapy resistance, Parker and colleagues investigated the effects of combining CK2 and BRAF inhibition." (PMID 40508214, 2025). "Experts use genetic markers and especially changes in BRAF and NRAS genes, to learn more about how melanoma develops and progresses." (PMID 41049012, 2025). "This pathway promotes the uncontrolled proliferation and survival of melanoma cells, making BRAF and MEK inhibitors essential components of targeted melanoma therapy." (PMID 40243953, 2025). "In BRAF- and NRAS-mutant melanoma patients, low ACKR2 expression or high CCL5/CXCL10 levels correlated with improved survival and higher CD8+ T cell markers." (PMID 40248897, 2025). "The search results revealed that a total of 3,503 documents related to BRAF and MEK inhibitor resistance in melanoma were indexed." (PMID 39897423, 2025). "Further advancing combination therapy, bioengineered nanogels (CDNPs) co-encapsulating BRAF and COX2 inhibitors induced melanoma cell pyroptosis—a highly ICD mode." (PMID 40861441, 2025). "However, we could rule out both pathways as drivers of constitutive IκBζ expression in melanoma, as neither the presence of activating BRAF or NRAS mutations nor increased NF-κB activity correlated with constitutive IκBζ protein expression." (PMID 40562773, 2025). "Nevertheless, resistance to BRAF and MEK kinase inhibitors is nearly always developed in BRAF (V600E) mutant melanomas." (PMID 40240755, 2025). "Although trametinib is known to be highly effective against BRAF/NRAS wild-type melanoma, its sensitivity in NF1-negative melanoma cell lines is comparable to that in NF1-expressing lines, suggesting that further research is required." (PMID 41001300, 2025). "Furthermore, upregulated of ROS related signatures are observed in residual tumors from TKI‐treated patients with EGFR+ NSCLC, HER2+ breast cancer, and BRAF+ melanoma, suggesting that the findings of our study with ALK+ NSCLC cells may also possibly be observed in patients with ALK+ NSCLC." (PMID 39369284, 2025). "In patient-derived melanoma cells with innate or clinically acquired resistance to MAPK inhibitors, ARF6 inhibition enhanced sensitivity to combined BRAF + MEK inhibition." (PMID 40909781, 2025). "BRAF/MEK-targeted therapies and immune checkpoint inhibitors have remarkable success against melanoma." (PMID 41271646, 2025). "Recent treatment breakthrough including BRAF/MEK-targeted therapies and immune checkpoint inhibitors (ICIs) have improved survival in advanced melanoma, but approximately half of patients fail to achieve long-term benefit." (PMID 41425556, 2025). "Top 10 co-cited references with the highest centrality in BRAF and MEK inhibitor resistance research in melanoma." (PMID 39897423, 2025). "Until 2011, the treatment options for brain metastases from melanoma (MBM) were radiation and neurosurgery (i.e., local therapies) or BRAF‐targeted therapy." (PMID 40485242, 2025). "Specifically, Nrf2 has been identified as a critical factor contributing to resistance against BRAF and MEK inhibitors in melanoma cells." (PMID 41085102, 2025).